CDK1 (cyclin dependent kinase 1)
Diseases named in the same sentence as CDK1 in open-access papers (continued):
Sharing a sentence is not in itself a finding about the gene and the disease.
triple-negative breast carcinoma (20 papers, 2014 to 2025). An invasive breast carcinoma which is negative for expression of estrogen receptor (ER), progesterone receptor (PR), and human epidermal growth factor receptor 2 (HER2). "For example, YOD1 stabilizes CDK1 through deubiquitination, promoting tumorigenesis in triple-negative breast cancer." (PMID 40534847, 2025). "An inhibition of CDK1 is able to suppress tumor growth and induce apoptosis in triple-negative breast cancer." (PMID 31428132, 2019). "Targeting CDK1 or its downstream signaling pathways may offer novel strategies, particularly for aggressive subtypes such as Basal-like or triple-negative breast cancer." (PMID 41278293, 2025). "In triple-negative breast cancer models, KLT effectively blocked cell cycle progression at the G2/M phase by downregulating CDK1, CDK2, and CHEK1, inhibiting CDC25A, CDC25B, MELK, and AURKA activity, suppressing mitosis, and inducing apoptosis." (PMID 41164166, 2025). "In Myc-overexpressing triple-negative breast cancer (TNBC) xenografts, inhibition of cyclin-dependent kinase 1 (CDK1) with dinaciclib leads to synthetic lethality and attenuates distant metastasis." (PMID 37669923, 2023). "A study conducted by Ju indicated that the inhibition of eEF2K, with the glutamine starvation, induces cyclin-dependent kinase 1 (CDK1) and 6 (CDK6), which then suppress the growth of triple-negative breast cancer." (PMID 34532346, 2021). "In triple-negative breast cancer, USP29 was recently reported to be phosphorated and activated by cyclin-dependent kinase 1 (CDK1), and then deubiquitinate and stabilize twist family bHLH transcription factor 1 (TWIST1), which is a key regulator of epithelial-mesenchymal transition." (PMID 38233848, 2024). "Here, we identify cyclin-dependent kinase 1 (CDK1) and peptidyl-prolyl cis-trans isomerase NIMA-interacting 1 (PIN1) as two previously uncharacterized regulators of pVHL in multiple types of human cancers harboring wild-type VHL including triple-negative breast cancer (TNBC)." (PMID 36813923, 2023). "Moreover, CDK1 may interfere with the synthetic lethality of other oncogenes, such as MYC in triple-negative breast cancer, PARP and PI3-kinase." (PMID 32948832, 2021). "These tumors exhibit elevated c-MYC expression, and the authors used CDK1 siRNA delivered by cationic lipid assisted nanoparticles to induce decreased cell viability and apoptosis only in c-MYC overexpressed triple-negative breast cancers and not in normal mammary epithelial cells." (PMID 28855742, 2017).
COVID-19 (16 papers, 2022 to 2025). A disease caused by infection with severe acute respiratory syndrome coronavirus 2. "CDK1 is highly expressed in PBMCs of COVID-19 patients and is involved in the apoptosis process; CDK1 may also be associated with a worsening of the course of COVID-19, which is characterized by an extreme decrease in immune cells." (PMID 39371335, 2024). "Among the ten candidate hub genes, we found that 8 hub genes were differentially upregulated in HBV and COVID-19, so we further narrowed the scope of the study to 8 hub genes, including CDK1, E2F7, E2F8, TYMS, KIF20A, CENPE, TPX2, HMMR." (PMID 40408617, 2025). "The abnormal expression of CCNB1 and CDK1 indicated that the cell cycle and proliferation was dysregulated in COVID-19." (PMID 40300201, 2025). "The GSE167028 and GSE150392 datasets were subjected to a recent bioinformatic analysis, which unveiled six critical genes (CDK1, KIF20A, PBK, KIF2C, CDC20, and UBE2C) associated with COVID-19 myocarditis." (PMID 40230577, 2025). "A previous observational study has suggested that CCNB1 and CDK1 is the hub regulatory genes in the pathogenesis of COVID-19 and highly expressed in COVID-19." (PMID 40300201, 2025). "CDK1 is highly expressed in PBMCs of COVID-19 patients, and it is involved in the process of apoptosis; it may also be related to the deterioration of the course of COVID-19, characterized by the extreme reduction of immune cells." (PMID 36551164, 2022). "Similarly, in previous studies, CDK1 was identified as a potential target of COVID-19, so the role of CDK1 in myocarditis needs to be further investigated." (PMID 35749386, 2022). "Therefore, Cyclin A2 may be another potential target for the treatment of COVID-19 and IS through the mechanism of affecting the level of cyclin B1/CDK1." (PMID 37184686, 2023). "Therefore, in this context, dysregulation of cyclin B1/CDK1 complex activity may be one of the mechanisms by which patients with COVID-19 are complicated with IS and affect the prognosis." (PMID 37184686, 2023). "Subsequently, CDK1 inhibition may offer a therapeutic strategy to fight COVID-19." (PMID 35831333, 2022). "Therefore, CDK1 may up-regulate the expression in critically ill patients, and researchers also found that RdRP inhibitors have a positive therapeutic effect on COVID-19 patients." (PMID 36551164, 2022). "However, the mouse pneumonia model shows different results, and researchers found that CDK1 is significantly up-regulated during the recovery of lung infections, which means that mild non-COVID-19 cases may have higher CDK expression levels." (PMID 36551164, 2022). "The six biomarkers (CCNB1, CDK1, IRF4, LTA, MMP9 and OSM) can be served as the biomarkers for the treatment and prevention of COVID-19." (PMID 40300201, 2025). "The expressions of CCNB1, CDK1, IRF4, MMP9 and OSM were significantly higher in COVID-19 samples compared with matched controls, while LTA was down-regulated in GSE171110 training dataset." (PMID 40300201, 2025). "Consistent with the bioinformatic analysis, CCNB1, CDK1, IRF4, MMP9 and OSM were significantly overexpressed, while LTA was de-expressed in COVID-19 patients compared with healthy controls." (PMID 40300201, 2025). "The targeting of CDK1 and TTK by curcomol provides an opportunity to treat patients with LUAD and COVID-19." (PMID 35520289, 2022). "Eventually, 6 genes (CDK1, KIF20A, PBK, KIF2C, CDC20, UBE2C) were identified by CytoHubba plug-in of Cytoscape as critical genes of COVID-19 Myocarditis for future study." (PMID 35749386, 2022). "The network pharmacology analysis identified seven core targets (namely, AURKA, CDK1, CCNB1, CCNB2, CCNE1, CCNE2, and TTK) of curcumol in patients with COVID-19 and LUAD." (PMID 35520289, 2022). "Based on 5 algorithms of the CytoHubba plug-in, six genes (CDK1, KIF20A, PBK, KIF2C, CDC20, UBE2C) were confirmed as critical genes related to COVID-19 Myocarditis." (PMID 35749386, 2022).
COVID-19 (continued). "We identified seven core pharmacological targets of curcumol, namely, AURKA, CDK1, CCNB1, CCNB2, CCNE1, CCNE2, and TTK, in treating LUAD and COVID-19." (PMID 35520289, 2022). "The molecular network analysis using Cytoscape highlighted seven core targets of curcumol, namely, AURKA, CDK1, CCNB1, CCNB2, CCNE1, CCNE2, and TTK in COVID-19 and LUAD." (PMID 35520289, 2022). "In this context, ACTIN suggested that CDK1/5 inhibitors and JANEX-1 could potentially serve as novel therapeutic agents for severe COVID-19 cases." (PMID 39017949, 2024). "It is worth highlighting that critical genes (CDK1, KIF20A, PBK, KIF2C, CDC20, UBE2C) may be potential biomarkers and treatment targets of COVID-19 Myocarditis for future study." (PMID 35749386, 2022). "Based on topological algorithms (i.e., degree), in this study, CDK1, KIF20A, PBK, KIF2C, CDC20, and UBE2C were identified as critical genes that may be potential biomarkers for COVID-19 Myocarditis." (PMID 35749386, 2022).
oral squamous cell carcinoma (16 papers, 2015 to 2025). "The activation of the CDK1-cyclin B1 complex leads to mitotic entry, and overexpression of cyclin B1 and CDK1 proteins is associated with progression of human oral squamous cell carcinoma." (PMID 26110572, 2015). "For instance, CASC2 alleviated the growth and metastasis of oral squamous cell carcinoma via down-regulating cyclin-dependent kinase 1 (CDK1), a key player in cell cycle regulation." (PMID 32206065, 2020). "The cyclin/CDK1/CKI pathway was found to affect cell cycle distribution and proliferation of human oral squamous cell carcinoma cells." (PMID 35246013, 2022). "Key words:Cyclin-dependent kinase 1 (CDK1), oral squamous cell carcinoma (OSCC), immunohistochemistry, cell proliferation." (PMID 25129248, 2015). "Interestingly, in oral squamous cell carcinoma (OSCC), the expression of CDK1 increases with the progression of tumor stage, but the expression of CDK1 is reduced at the stage IV and late stage of the tumor." (PMID 30838018, 2019).
acute myeloid leukemia (15 papers, 2015 to 2025). Acute myeloid leukemia (AML) is a group of neoplasms arising from precursor cells committed to the myeloid cell-line differentiation. "Targeting CDK1 has been reported to promote FLT3-activated acute myeloid leukemia differentiation in cell lines as well as in patient blood samples." (PMID 34067359, 2021). "CDK1 expression was significantly higher in the bone marrow from acute myeloid leukemia (AML) patients at recurrence than that at initial diagnosis." (PMID 32596342, 2020). "CDK1 inhibitors have great potential in inducing degradation and apoptosis of YTHDF2 in acute myeloid leukemia (AML)." (PMID 40919129, 2025). "AT-7519 is the second generation multi-CDK inhibitor that targets CDK1/2/4/6/9 and has proven effective in inhibiting hematologic malignancies, while BMS-387032 is a selective CDK2 inhibitor that has shown promise in treating acute myeloid leukemia in vitro." (PMID 35205315, 2022).
endometrial cancer (15 papers, 2014 to 2025). Primary or metastatic malignant neoplasm involving the endometrium (mucous membrane that lines the endometrial cavity). "The inhibition of CDK1 activity induced cell apoptosis and caused the G2/M phase arrest of cell cycle in endometrial cancer cells." (PMID 35883603, 2022). "The inhibition of CDK1 activity induced cell apoptosis and caused G2/M phase arrest of cell cycle in endometrial cancer cells." (PMID 33758599, 2021). "In addition, cytoplasmic CDK1 expression is associated with histological grade (the degree of differentiation) of endometrial cancer." (PMID 33758599, 2021). "miR-1271 overexpression inhibits the proliferation of endometrial cancer cells and induces apoptosis by targeting CDK1." (PMID 36699068, 2022). "CDK1 inhibitor, RO3306, induced cell apoptosis and caused G2/M phase arrest of the cell cycle in endometrial cancer cells." (PMID 35883603, 2022). "CDK1 was screen out to be one of the hub genes in the development of endometrial cancer by our study." (PMID 33758599, 2021). "Cytoplasmic CDK1 is more frequently expressed higher in G2 endometrial endometrial cancer than that in G1 endometrial endometrial cancer." (PMID 33758599, 2021). "Previous studies revealed that many factors such as progestin, miRNA, adipocyte and urolithin A, inhibited the tumorigenicity of endometrial cancer cells by targeting CDK1 20-27." (PMID 33758599, 2021). "Similar to our finding, CDK1 was found to be over expressed in human endometrial cancer tissues by other researches 39-41." (PMID 33758599, 2021). "An important finding by our study was that CDK1 promoted endometrial cancer cell growth and colony formation in vitro." (PMID 33758599, 2021). "Cell viability and colony formation were used to study the effects of CDK1 on the proliferation and colony formation of endometrial cancer cells in vitro." (PMID 33758599, 2021). "Tumor xenograft transplantation assay was performed to show the effects of CDK1 on the growth of endometrial cancer cells in vivo." (PMID 33758599, 2021). "CDK1 was found to be one of the hub genes in the development of endometrial cancer using different databases 32-35." (PMID 33758599, 2021). "The cytoplasmic CDK1 expression in Grade 1 (well differentiated) endometrial cancer tissues was lower than that in Grade 2 (moderately differentiated) endometrial cancer tissues." (PMID 33758599, 2021). "MicroRNA-1271 was increased in endometrial cancer and reduced proliferation by inhibiting CDK1 expression." (PMID 33178832, 2020). "In endometrial cancer cells, miRNA302 inhibits cell proliferation and migration, induces apoptosis, attenuates invasiveness by inhibiting cyclin D1 and CDK1, and arrests the cell cycle in the G2/M phase." (PMID 32760226, 2020). "MiRNA-302 inhibits the tumorigenicity of endometrial cancer cells by suppressing cyclin D1 and CDK1." (PMID 30326936, 2018). "The role of CDK1 in gynecological cancer is limited to ovarian and endometrial cancer." (PMID 35883603, 2022). "The inhibition of CDK1 activity also inhibited endometrial cancer growth in xenograft models." (PMID 33758599, 2021). "Inhibition of the activity of CDK1 could inhibit the growth of endometrial cancer cells in vitro and in vivo." (PMID 33758599, 2021). "In addition, CDK1 expression in endometrial cancer tissues was also significantly higher than that in matched adjacent normal endometrium tissues (p < 0.0001)." (PMID 33758599, 2021). "CDK1 promoted endometrial cancer cell growth and colony formation in vitro." (PMID 33758599, 2021). "Therefore, the elevation of CDK1 expression in the nucleus and cytoplasm was important for the pathogenesis of endometriold endometrial cancer." (PMID 33758599, 2021). "Immunohistochemistry was used to verify the expression of CDK1 in endometrial cancer tissue." (PMID 33758599, 2021).
endometrial cancer (continued). "Overexpression of lncRNA ABHD11‐AS1 promoted the proliferation, G1‐S progression, invasion and migration of endometrial cancer cells; inhibited apoptosis; up‐regulated cyclin D1, CDK1, CDK2, CDK4, Bcl‐xl and VEGFA; and down‐regulated p16, while ABHD11‐AS1 down‐regulation has the opposite effect." (PMID 29799152, 2018). "In vitro and in vivo, CDK1 could promote the growth and proliferation of endometrial cancer cells." (PMID 33758599, 2021). "The results showed that the expression of CDK1, CALM2, and SIRT4 was significantly increased in all grades of endometrial cancer compared to the control group." (PMID 34768392, 2021).
neuroblastoma (15 papers, 2015 to 2024). Neuroblastoma (NB) is the most common solid, extracranial childhood tumor. "CDK1 inhibition resulted in elevation of miR-34a, meanwhile miR-34a suppression up-regulated the expression of MYCN and enhanced cell survival of neuroblastoma cells treated with CDK1 antagonist." (PMID 33773546, 2021). "Here we show that FL BARD1, as part of the heterodimer BRCA1/BARD1, prevent unscheduled mitotic entry of DNA damaged neuroblastoma cells via a mechanism requiring downregulation of cyclin B/Cdk1 and cell cycle arrest at the G2-M boundary." (PMID 32047556, 2020). "In this study, it was demonstrated that O2/O3 treatment was able to reduce cell growth and to arrest cell cycle at G2 phase, by inhibiting the expression and localization of cyclin B1/cdk1 in neuroblastoma cell lines." (PMID 32992648, 2020). "We showed here that PKMYT1 is required to stabilize the MYCN protein in neuroblastoma cells by reducing T58 phosphorylation by the cdk1/gsk3 kinases, explaining the synthetic lethal effect of PKMYT1 inactivation in MYCN-amplified cells." (PMID 25477524, 2015). "Transient downregulation of CCNB1 or cdk1 was achieved by sequence-specific siRNAs in a panel of five neuroblastoma cell lines." (PMID 26029996, 2015). "Further, Lamin A phosphorylation on Serine 22 is required for CDK1-catalysed nuclear envelope disassembly, and we could previously show that CDK1 is upregulated in aggressive neuroblastoma independently of MYCN status." (PMID 34771457, 2021). "Used at low concentrations, Dinaciclib is a broad CDK inhibitor (CDK1, 2, 5, and 9), but its antagonistic effect on CDK2 and CDK9 has been attributed to its ability to suppress neuroblastoma cell proliferation." (PMID 33796454, 2021). "As previously reported, upregulation of cdks is common in aggressive neuroblastoma, but only CCNB1/cdk1 were predictive of outcome both in the entire cohort as well as in the MYCN normal group when the Cyclin/cdk pairs were considered." (PMID 26029996, 2015). "PLK-1, CDK-1, PIK3CA, ATF4, TEAD4 and ALYREF could enhance MYCN protein stability and sustain MYCN expression in neuroblastoma." (PMID 35820898, 2022). "In neuroblastoma cell lines, CDK/CDK1 inhibitors show an ability to downregulate MYC." (PMID 34638300, 2021). "Thus, MYCN is a sufficient but not necessary regulator of CCNB1/cdk1 expression, and upregulaton of CCNB1 and cdk1 is a common feature of neuroblastoma cell lines irrespective of their MYCN status." (PMID 26029996, 2015). "However, the high expression levels of cdk1/CCNB1 in cell lines with normal MYCN, which are also found in primary tumors in the absence of MYCN amplification, left us to conclude that MYCN is a sufficient but not a necessary driver of cdk1/CCNB1 in neuroblastoma cells." (PMID 26029996, 2015).
viral infection (14 papers, 2016 to 2026). "For example, genes such as AURKA and CDK1 have been previously implicated in cell cycle regulation during viral infections, consistent with our results." (PMID 40100920, 2025). "To validate this, we utilized mTOR and CDK1 inhibitors, which mimicked the effects of viral infection, resulting in increased LARP1 binding to viral RNA." (PMID 40294010, 2025). "Viral infection inhibits mTOR and CDK1 phosphorylation, which enhances LARP1’s binding to viral RNA and inhibits viral translation." (PMID 40294010, 2025). "Virus infection can reduce Cyclin B and CDK1 expression or inhibit Cyclin B1-CDK1 complex formation and nuclear import." (PMID 38793618, 2024). "It has been previously determined that during viral infection, the subcellular distribution of CDK1-cyclin B1 is altered, which is essential for the active CDK1-cyclin B1 to regulate virus replication." (PMID 36602364, 2023). "Notably, the C-terminal domain of the large subunit of RNA polymerase II (RNAPII), POLR2A, is extensively phosphorylated, and its phosphorylation is significantly reduced upon CDK1 inhibition during viral infection." (PMID 41827841, 2026). "However, CDK1 cannot be the sole regulator of SAMHD1 in MDM, as we also observed a modest downregulation of CDK1 protein by IFN-λ, which was not accompanied by significant protection from viral infection." (PMID 29764952, 2018).